OR1J4 (olfactory receptor family 1 subfamily J member 4)
Description:
Odorant receptor.
Synonyms: HTPCRX01; HSHTPCRX01; OR9-21
Tractability: Antibody: UniProt places it where antibodies can reach, with medium confidence; UniProt predicts a signal peptide or a membrane-spanning region; its Gene Ontology location is reachable by antibodies, with medium confidence.
Gene: Protein-coding gene on chromosome 9 (122,519,141 to 122,520,082, forward strand). Ensembl gene ENSG00000239590.
Subcellular location: Cell membrane
Pathways (Reactome):
Sensory Perception: Expression and translocation of olfactory receptors
Gene Ontology:
Molecular function: olfactory receptor activity; G protein-coupled receptor activity
Biological process: signal transduction; detection of chemical stimulus involved in sensory perception of smell; G protein-coupled receptor signaling pathway
Cellular component: plasma membrane; membrane
Genetic constraint (gnomAD): Loss-of-function variants: 0 observed, 0.52 expected, observed/expected ratio (o/e) 0, 90% interval 0 to 1.83. That is too few expected variants to judge how well the gene tolerates losing a copy. Missense variants: 350 observed, 390.38 expected, observed/expected ratio (o/e) 0.9, 90% interval 0.82 to 0.98. Synonymous variants: 154 observed, 161.03 expected, observed/expected ratio (o/e) 0.96, 90% interval 0.84 to 1.09.
Homologues: Orthologues: chimpanzee OR1J4 (99% identical), rabbit OR1J4 (85% identical), guinea pig OR1J4 (82% identical), macaque OR1J4 (81% identical), rat Or1j4 (80% identical), mouse Or1j4 (79% identical). Paralogues in human: OR1J2 (78% identical), OR1J1 (74% identical), OR1E1 (61% identical), OR1E2 (61% identical), OR1F1 (59% identical), OR7D2 (55% identical), OR7C2 (54% identical), OR1G1 (54% identical), OR7C1 (54% identical), OR1M1 (54% identical), OR1N1 (54% identical), OR1N2 (53% identical), and 116 more.
Diseases named in the same sentence as OR1J4 in open-access papers:
OR1J4 is named in the same sentence as 1 disease in open-access papers, as found by Europe PMC text mining. Sharing a sentence is not in itself a finding about the gene and the disease. The quoted sentences say what the papers report.
breast carcinoma (1 paper, 2024). "According to information from the KEGG database, we have discovered that in breast cancer, olfactory receptors such as OR11H6, OR1J4, OR4N5, and OR11G2O are associated with the olfactory transduction pathway." (PMID 38254021, 2024).